PNPLA6 (patatin like domain 6, lysophospholipase )
Diseases named in the same sentence as PNPLA6 in open-access papers:
PNPLA6 is named in the same sentence as 58 diseases in open-access papers, as found by Europe PMC text mining. Sharing a sentence is not in itself a finding about the gene and the disease. The quoted sentences say what the papers report.
Ataxia (21 papers, 2014 to 2025). Ataxia refers to impaired coordination of voluntary muscle movement. "Mutations in the human PNPLA6 gene are linked to rare inherited diseases termed PNPLA6-related disorders, with clinical symptoms including spastic paraplegia, ataxia, hypogonadism, and chorioretinal dystrophy, reminiscent of the OPIDN pathology." (PMID 36979406, 2023). "Cerebellar ataxia was described in 68% of the patients encompassing all the syndromes associated with PNPLA6." (PMID 35069422, 2021). "Mutations in patatin-like phospholipase domain-containing protein 6 (PNPLA6) have been linked with a number of inherited diseases with clinical symptoms that include spastic paraplegia, ataxia, and chorioretinal dystrophy." (PMID 31780887, 2019). "Mutations in the PNPLA6 gene have been identified as the cause of hereditary spastic paraplegia and complex forms of ataxia associated with retinal and endocrine manifestations in a field where the genotype-phenotype correlations are rapidly expanding." (PMID 26995604, 2017). "We identified for the first time PNPLA6 mutations associated with pure cerebellar ataxia in a large autosomal-recessive Parsi kindred." (PMID 26995604, 2017). "We recently described patients with Gordon-Holmes syndrome (IHH and cerebellar ataxia) due to inactivating PNPLA6 mutations." (PMID 27086651, 2016). "Mutations in the PNPLA6 gene can disrupt the enzymatic activity of PNPLA6, impairing synaptic connections in neuronal networks, leading to a range of diseases from intellectual disabilities to ataxia." (PMID 41282473, 2025). "Mutations in PNPLA6 are associated with a spectrum of neurodegenerative disorders, that present clinical features ranging from pure cerebellar ataxia to complex forms of ataxia associated with other symptoms." (PMID 35420383, 2022). "PNPLA6 variants cause a broad range of phenotypes, including HSP, ataxia, retinal, neuroendocrine, and cognitive manifestations." (PMID 36825042, 2023). "More recently, mutations in PNPLA6/NTE have been linked with a number of inherited diseases with diverse clinical symptoms that include spastic paraplegia, ataxia, and chorioretinal dystrophy." (PMID 35448471, 2022). "For instance, PNPLA6 has been identified as a cause of complicated HSP combined with motor neuropathy (SPG39), and it has also been linked to AR cerebellar ataxia." (PMID 36247768, 2022). "The description of patients presenting very late-onset cerebellar ataxia suggests that PNPLA6 genetic screening should also be considered in the diagnostic workout of adult cerebellar ataxia." (PMID 35069422, 2021). "Currently, POLR3A, POLR3B, OTUD4, STUB1, PNPLA6, and RNF216 are all genes associated with CHH syndromes and cerebellar ataxia, with clinical manifestations that can vary and may present with infant or adult onset." (PMID 40508017, 2025). "Pathogenic variants in the PNPLA6 gene were also demonstrated to cause the Laurence—Moon syndrome (LM, MIM 245800) that includes all the symptoms of the Oliver—Mc Farlane syndrome plus neurological symptoms, such as ataxia, spastic paraplegia, and neuropathy." (PMID 35069422, 2021). "Two index patients had a very late-onset cerebellar ataxia at age 47 (pt 7) and 55 (pt 8) and no additional PNPLA6-associated clinical features, in particular chorioretinal dystrophy or hypogonadotropic hypogonadism." (PMID 35069422, 2021). "Although comorbid spastic paraplegia and parkinsonism have been reported in PNPLA6-related disorders, the proband in this study has not yet developed these signs, exhibiting only mild gait instability, ataxia, and coordination disorders." (PMID 41321566, 2025).
Spastic paraplegia (12 papers, 2016 to 2025). Complete loss of the ability to move the lower limbs accompanied by spasticity of the lower limbs. "The same occurred with a PCYT2 mutation in patient IDSPG27, ranked 3 in a VCF file with 1738 variants, because PCYT2 protein interacts with other proteins associated with spastic paraplegia such as PNPLA6 or COASY." (PMID 37679823, 2023). "We describe a large kindred with a novel clinical phenotype as, in addition to spastic paraplegia, affected subjects suffered from a prominent cerebellar oculomotor dysfunction with two hitherto undescribed mutations of PNPLA6." (PMID 35947152, 2022). "While PNPLA6 has been implicated in a variety of disorders, among which the leading manifestations are often extra-neural, spastic paraplegia as the leading or even sole manifestation has been described in only three case reports." (PMID 35947152, 2022). "Mutations in PNPLA6/NTE have now been identified in a few more spastic paraplegia patients and there are now also mutations outside the esterase domain." (PMID 35448471, 2022). "The first disease-causing mutations in PNPLA6/NTE were described in 2008 in two families with affected members showing progressive spastic paraplegia associated with distal upper and lower extremity wasting starting in childhood." (PMID 35448471, 2022). "Pathogenic variants in the PNPLA6 gene have been originally described in patients presenting a neurological phenotype characterized by early-onset spastic paraplegia, motor neuropathy, and distal muscle wasting." (PMID 35069422, 2021).
Boucher–Neuhäuser syndrome (10 papers, 2014 to 2025). "The novel variants in the PNPLA6 gene related to Boucher–Neuhäuser syndrome were summarized in this article." (PMID 35198007, 2022). "Mutations in the PNPLA6 (patatin like phospholipase domain containing 6) gene cause SPG39 and Boucher–Neuhäuser syndrome which express similar symptoms." (PMID 33917666, 2021). "Furthermore, a list of the PNPLA6 variants associated with Boucher–Neuhäuser syndrome has been compiled and reviewed." (PMID 35198007, 2022). "Boucher–Neuhäuser syndrome (BNS) is a rare autosomal recessive disorder that often develops at a young age and is caused by mutations in the PNPLA6 gene." (PMID 35198007, 2022). "PNPLA6 gene mutations cause hereditary spastic paraplegia (SPG39 HSP), Gordon-Holmes syndrome, Boucher-Neuhäuser syndromes, Laurence-Moon syndrome, and Oliver-McFarlane syndrome." (PMID 26671664, 2015).
Gordon-Holmes syndrome (10 papers, 2015 to 2025). "The PNPLA6 gene is implicated in several neurodegenerative conditions, including Gordon–Holmes syndrome, Boucher–Meuhäuser, spastic paraplegia type 39, Laurence–Moon, and Oliver–McFarlane syndrome." (PMID 38891946, 2024). "It thus resembles also other genes which cause Gordon Holmes syndrome as part of a multisystemic disease spectrum, e.g. PNPLA6." (PMID 28193273, 2017). "It adds further support of STUB1 as one important cause of Gordon Holmes syndrome, which shows a substantial genetic heterogeneity as it can also be caused by mutations in e.g. PNPLA6." (PMID 28193273, 2017). "In recently years, more and more human NTE/PNPLA6 mutations have been identified to be linked to various complex nervous system diseases, such as hereditary spastic paraplegia 39 (SPG39), Boucher–Neuhäuser syndrome, Gordon–Holmes syndrome, Oliver–McFarlane syndrome and Laurence–Moon syndrome." (PMID 35888761, 2022).
hypogonadotropic hypogonadism (8 papers, 2017 to 2024). Abnormal ovarian or testicular function due to insufficient hormonal stimulation from the hypothalamic-pituitary axis. "In conclusion, novel compound heterozygous variants in the PNPLA6 gene were identified through whole-exome sequencing and validated by RNA-Seq and qRT-PCR in a patient with retinitis pigmentosa and hypogonadotropic hypogonadism." (PMID 35198007, 2022). "The hitherto undescribed (compound heterozygous) PNPLA6 variants were accompanied by a novel clinical phenotype comprising prominent dysfunction of cerebellar oculomotor structures and the upper motor neuron system as well as some degree of hypogonadotropic hypogonadism." (PMID 35947152, 2022). "Hypogonadotropic hypogonadism was found in 74% of cases and has been detected in all PNPLA6-associated phenotypes except in SPG39." (PMID 35069422, 2021). "Other features of PNPLA6 related syndromes such as chorioretinal dystrophy, peripheral neuropathy, and hypogonadotropic hypogonadism were absent." (PMID 36825042, 2023).
hereditary spastic paraplegia (6 papers, 2015 to 2023). Hereditary spastic paraplegias (HSP) comprise a genetically and clinically heterogeneous group of neurodegenerative disorders characterized by progressive spasticity and hyperreflexia of the lower limbs. "Mutations in the patatin-like phospholipase domain-containing protein 6 (PNPLA6) gene were originally described in 2008 as causative for specific forms of complicated hereditary spastic paraplegia (SPG39, MIM#612020)." (PMID 26995604, 2017).
hypogonadism (6 papers, 2014 to 2023). A disorder characterized by decreased function of the gonads. "With an upper motor neuron disorder, isolated oculomotor cerebellar dysfunction and a limited degree of hypogonadism we add a novel phenotype that is likely to be caused by the detected variants of PNPLA6." (PMID 35947152, 2022). "In recent years, mutations in PNPLA6/NTE have also been linked with a number of rare inherited diseases with clinical symptoms that can include spastic paraplegia, ataxia, hypogonadism, and chorioretinal dystrophy." (PMID 35448471, 2022).
Oliver-McFarlane syndrome (6 papers, 2015 to 2025). "We report a case from China of PNPLA6 gene variants leading to Oliver-McFarlane syndrome, with the patient exhibiting typical characteristics of OMCS." (PMID 41282473, 2025). "Here, we report a case of Oliver-McFarlane syndrome caused by PNPLA6 gene mutations from China." (PMID 41282473, 2025).
neuropathy (5 papers, 2008 to 2022). A disorder affecting the nervous system that manifests with pain, tingling, numbness, and/or muscle weakness. "Fat metabolism and its link in axonal growth, neuropathy target esterase PNPLA6/SPG39, essential for the generation of axons in the long spinal cord, and the CYP7B1/SPG5 gene play a fundamental role in the metabolism of cholesterol." (PMID 35887006, 2022). "Patatin-like phospholipase domain-containing protein 6 (Pnpla6) is a neuropathy target esterase enzyme that deacetylates intracellular phosphatidylcholine (PE) to produce glycerophosphocholine (GPC)." (PMID 27006086, 2016). "In this respect, PNPLA6 is inhibited by organophosphate compounds, leading to delayed neuropathy in man and chicken." (PMID 18549477, 2008).
hereditary spastic paraplegia 39 (4 papers, 2018 to 2025). This syndrome is characterized by progressive spastic paraplegia and distal muscle wasting. "Mutations in PNPLA6 cause Hereditary Spastic Paraplegia 39 (OMIM #612020), but levodopa-responsive parkinsonism has been reported in association with biallelic mutations, generally with additional clinical features." (PMID 39420034, 2024). "Mutations in the human patatin-like lysophospholipase domain containing the 6 gene PNPLA6 encode an evolutionarily conserved (lyso)phospholipase, leading to the development of a complex hereditary spastic paraplegia 39 (SPG 39) and a number of rare severe syndromes in humans." (PMID 41303565, 2025).
Parkinsonism (3 papers, 2023 to 2025). Characteristic neurologic anomaly resulting from degeneration of dopamine-generating cells in the substantia nigra, a region of the midbrain, characterized clinically by shaking, rigidity, slowness of movement and difficulty with walking and gait. "Our case adds to a prior report of levodopa‐responsive parkinsonism, and provides further evidence supporting the pathogenicity of PNPLA6 variant c.4003C > T (p.Pro1335Ser)." (PMID 36825042, 2023). "This case further supports the manifestation of treatment‐responsive parkinsonism with PNPLA6 variants." (PMID 36825042, 2023). "Our case further supports levodopa‐responsive parkinsonism due to PNPLA6 variants." (PMID 36825042, 2023). "Defects in many of these mechanisms have already been implicated in the pathogenesis of parkinsonism, making the manifestation of early onset parkinsonism in the spectrum of PNPLA6‐related phenotypes not unexpected." (PMID 36825042, 2023).
retinal degeneration (3 papers, 2021 to 2025). Degeneration of the retina. "This could cause retinal degeneration due to PNPLA6 mutations." (PMID 35198007, 2022).
aneurysm (2 papers, 2022 to 2025). Bulging or ballooning in an area of an artery secondary to arterial wall weakening. "Hypomethylation of several genes, including CXCR4, OSM, GSTA4, MAP3K10, ADAMTS, PTBP1, and PNPLA6,61, –63,65,67,71 has been identified as being associated with the aneurysm formation." (PMID 41342741, 2025).
Cerebellar atrophy (2 papers, 2022 to 2025). Cerebellar atrophy is defined as a cerebellum with initially normal structures, in a posterior fossa with normal size, which displays enlarged fissures (interfolial spaces) in comparison to the foliae secondary to loss of tissue. "Neurological and imaging abnormalities are also reported in PNPLA6-related disorders, including white matter signal changes, pituitary and cerebellar atrophy, and empty sella turcica." (PMID 41321566, 2025).
choroideremia (1 paper, 2025). Choroideremia (CHM) is an X-linked chorioretinal dystrophy characterized by progressive degeneration of the choroid, retinal pigment epithelium (RPE) and retina. "He found that one allele or biallelic variant in the patatin-like phospholipase domain is highly associated with choroideremia and more patients with severe harmful PNPLA6 variants exhibit choroideremia." (PMID 41282473, 2025).
mast syndrome (1 paper, 2015). "Such conditions include HSP with thin corpus callosum (SPG11/15 mutations), SPG35/FA2H-associated HSP, Troyer syndrome (SPG20) and Mast syndrome (SPG21), SPG26/B4GALNT1, SPG30/KIF1A, SPG39/PNPLA6 and SPG46/GBA2." (PMID 25480570, 2015).
polyneuropathies (1 paper, 2024). "Among these, PNPLA6 and RBMX are described in polyneuropathies and neurological disorders." (PMID 39409151, 2024).
ZIKV infection (1 paper, 2018). "Specifically, we observed that the FMRP targets, FXR2, TLN1, BRD4, and PNPLA6 were elevated at the protein level as a consequence of ZIKV infection." (PMID 30511641, 2018).
cancer (4 papers, 2017 to 2023). A tumor composed of atypical neoplastic, often pleomorphic cells that invade other tissues. "In lean NASH-HCC, methylation differences were seen in genes involved with cancer progression and prognosis (including HCC), such as CHCHD2, FSCN1, and ZDHHC12, and lipid metabolism, including PNPLA6 and LDLRAP1." (PMID 36474183, 2022). "However, the other two genes, LDLRAP1 and PNPLA6, have not been found to be related to cancer patients’ prognosis at present." (PMID 35957912, 2022).
neurological disorders (4 papers, 2015 to 2025). "In fact, it has now been shown that mutations in PNPLA6/NTE can cause a wide spectrum of neurological disorders with overlapping symptoms, which have now been categorized as PNPLA6-related disorders." (PMID 35448471, 2022). "Most of the 313 new disease links belonged to the DisGeNET class neoplasms (n = 40; EGFR, ERBB2, KITLG, AREG) but also to immune diseases (n = 29; FAS), neurological diseases (n = 13; PNPLA6), and cardiovascular diseases (n = 13; CD163)." (PMID 40593564, 2025).
neurodegenerative disease (3 papers, 2019 to 2023). A disorder of the central nervous system characterized by gradual and progressive loss of neural tissue and neurologic function. "Pathogenic variants in the PNPLA6 gene(-encoding patatin-like phospholipase domain containing protein 6) have been demonstrated to cause a number of variable neurodegenerative diseases." (PMID 35069422, 2021). "A wide spectrum of neurodegenerative diseases has been associated with pathogenic variants in the PNPLA6 (patatin-like phospholipase domain-containing protein 6) gene, including spastic paraplegia type 39, Gordon—Holmes, Boucher—Neuhauser, Oliver—Mc Farlane, and Laurence—Moon syndromes." (PMID 35069422, 2021).
tumor (3 papers, 2023 to 2025). "According to GEPIA, iPLA2β/PLA2G6 expression is downregulated in 15 tumor types, whereas iPLA2δ/PNPLA6 expression is only downregulated in three types." (PMID 36765904, 2023). "In human HCC (obtained from patients who had been treated in the Hepatobiliary Pancreatic Division, Department of Surgery, the University of Tokyo Hospital), the expression levels of PNPLA7 and PNPLA8, but not PNPLA6 and PNPLA9, were significantly lower in tumor tissues than in non-tumor tissues." (PMID 36979406, 2023).
infection (2 papers, 2018 to 2022). The state of being infected such as from the introduction of a foreign agent such as serum, vaccine, antigenic substance or organism. "At 6 days post-infection, protein expression levels of FXR2 and PNPLA6 [a validated FMRP target] were measured in testes." (PMID 30511641, 2018). "Measurements of viral genomes indicated a higher burden of infection for the WT virus than Δ10 ZIKV which may contribute to the differential effects on FXR2 and PNPLA6 levels." (PMID 30511641, 2018).
inherited diseases (2 papers, 2019 to 2022). "Mutations in PNPLA6/NTE can cause a spectrum of inherited diseases that, although showing overlapping phenotypes, also manifest distinct features." (PMID 35448471, 2022).
retinal disorder (2 papers, 2020 to 2025). Any disease or disorder of the retina. "This suggests choline modulation as a promising therapeutic strategy for PNPLA6-associated retinopathy, though further research is needed." (PMID 41321566, 2025).
central nervous system disorder (1 paper, 2022). A disease involving the central nervous system. "PNPLA6 mutations play crucial roles in the central nervous system disorders." (PMID 35957912, 2022).
PNPLA6 also shares sentences with these, for which no sentence is quoted: cerebellar ataxia (9 papers); Laurence-Moon syndrome (6); cardiovascular disease (2); amyotrophic lateral sclerosis (1); autosomal recessive cerebellar ataxia (1); coenzyme Q10 deficiency (1); cognitive decline (1); Cognitive impairment (1); congenital hypopituitarism (1); embryonal carcinoma (1); empty sella turcica (1); endometrial cancer (1); frontotemporal dementia (1); Gait ataxia (1); hepatoma (1); Hypodontia (1); immune diseases (1); intellectual disabilities (1); intracranial aneurysm (1); Juvenile onset (1); lung carcinoma (1); Motor neuron disease (1); Nystagmus (1); peripheral neuropathy (1); Primary amenorrhea (1); Retinal dystrophy (1); retinitis pigmentosa (1); skin cancer (1); spastic ataxia (1); Spasticity (1).
A further 2 diseases each share a sentence with PNPLA6 in 1 paper.